CD63 (CD63 molecule)
Diseases named in the same sentence as CD63 in open-access papers (continued):
Sharing a sentence is not in itself a finding about the gene and the disease.
pancreatic cancer (22 papers, 2018 to 2026). "Immunofluorescence experiments showed that CD63 was significantly aggregated in pancreatic cancer intracellularly after knockdown of Exo70 or ES2 treatment." (PMID 38254825, 2024). "sEVs labeled TSPAN8 and other tetraspanins (e.g., CD9 and CD63) are highly expressed in pancreatic cancer cells." (PMID 34980146, 2022). "TIMP1 activated hepatic stellate cells via CD63 signaling to create a premetastatic niche in pancreatic cancer." (PMID 35281807, 2022). "Plasmid transfection established stable pancreatic cancer cell lines expressing CD63-GFP (gPANC1) or CD63-RFP (rPANC1)." (PMID 34832842, 2021). "In pancreatic cancer, the expression of CD63 has been reported to be higher in cancerous tissues than in normal tissues." (PMID 30222750, 2018). "Pancreatic cancer TIMP1 stimulates neutrophils to release NETs via activating CD63-ERK pathway." (PMID 34868992, 2021). "Results using the ExoScreen assay from the same group showed that detection of CD145/CD9 dual positive cancer EVs is possible using 5 μL serum of colorectal cancer patients, and that EVs positive for GPRC5C/CD63 can discriminate pancreatitis patients from stage II pancreatic cancer." (PMID 31162490, 2018). "Conventional vesicles have high concentrations of tetraspanin proteins such as CD63, CD9, and CD81, in addition to Hsp70, which is a pancreatic cancer-specific marker that has also been reported in the exosomal or extravesicular population." (PMID 36002889, 2022).
glioma (20 papers, 2018 to 2025). A benign or malignant brain and spinal cord tumor that arises from glial cells (astrocytes, oligodendrocytes, ependymal cells). "Possibly,the subpopulations of TNC+/CD63+ EVs may primarilyoriginate from tumor-infiltrating immune cells, since CD63 has been shown to be upregulated in glioma-associatedmacrophages, and its mRNA was herein observedto colocalize with tumor-infiltrating myeloid cells." (PMID 40056466, 2025). "In this study, we performed immunofluorescent staining for CD63, a known EV marker, on a primary glioma patient-derived cell line and we used a STED microscopy platform to demonstrate EV secretion directly in cultured cells." (PMID 40703028, 2025). "Western blot analysis of plasma-derived exosomal proteins profiling of CD63 exosomal marker was visualized in different grades of glioma as depicted." (PMID 34900729, 2021). "Nanoparticle tracking analysis, western blot, and flow cytometry were performed to determine the size, morphology, the concentration of glioma-derived vesicles and EV marker, CD63." (PMID 34900729, 2021). "In contrast, the increase of FASN+/CD63+ EVs in glioma patients was mainly due to augmentation of the double positive EV population as a whole." (PMID 32178271, 2020). "Western blots were employed to demonstrate the expression of the exosome markers CD63 and Flotillin-1 in glioma patients' and normal donors' plasma exosomes isolated by two-step DGU." (PMID 31380286, 2019). "The flow cytometric assay revealed good levels of signals for the tetraspanin molecule CD63 tested as exosomal marker on vesicles derived from different-grade glioma patients (grade I, II, III), and the same proteins were detected by flow cytometry in control sample (healthy individuals)." (PMID 34900729, 2021). "Only few studies have investigated the presence of CD63 in gliomas." (PMID 29523123, 2018). "Only few studies describe the presence of CD63 protein in gliomas using immunohistochemistry." (PMID 29523123, 2018). "Performing immunostaining for CD63, a known exosome marker, and using STED microscopy, we demonstrate exosome secretion in primary glioma cells." (PMID 40703028, 2025). "Both CD63 and Flotillin-1 were detected in normal donors, grade 4 GBM and grade 3 glioma patients' exosomes, indicating again that our DGU protocol allows the isolation of exosomes." (PMID 31380286, 2019). "This targeting ability is attributed to specific surface moieties retained from the parent cells, including tetraspanins (CD9, CD63, CD81), integrins (e.g., αvβ3, α6β4), and phosphatidylserine, which interact with overexpressed receptors on the glioma endothelium and tumor cells." (PMID 40725021, 2025). "Here we identified fatty acid synthase (FASN), a key lipogenic enzyme which is highly expressed in malignant glioma cells, to be elevated in CD63- and CD81-positive EVs in glioma patient plasma samples, opening vital opportunities to sort brain tumor-specific EVs." (PMID 32178271, 2020). "In glioma, a study exploring EVs released by proneural, and mesenchymal glioma stem cells (GSCs) identified that proneural GSC-derived EVs lacked canonical EV-based tetraspanin markers such as CD9, CD63, and CD81, while they were abundant in mesenchymal GSC-derived EVs." (PMID 38760427, 2024).
viral infection (19 papers, 2016 to 2025). "Increased CD63 expression in CCoV-infected EVs could further assist in immune-associated communication, as CD63 is linked with EV-mediated immunological regulation in viral infections." (PMID 40431570, 2025). "We have previously demonstrated that WT virus infection triggers increased production of EVs through the CD63 biogenesis pathway." (PMID 40990523, 2025). "The tetraspanin CD63 is involved with exosome formation and plays an important role in viral infections such as hepatitis B infection." (PMID 36845728, 2023). "Remarkable upregulation of LC3 and CD63 indicated autophagy, and exosomes were obviously activated by virus infection." (PMID 35371077, 2022). "Arthropod CD63 ortholog Tsp29Fb has been recently described as a target for this type of therapies in viral infection." (PMID 33968023, 2021). "Viral infection induced a significant increase in the average number of Rab27a- or CD63-specific punctate structures in type III cells." (PMID 34214032, 2021). "Expression of these genes is associated with movement (MMP9, SPP1, ALCAM, and others), viral infection (APOC1, LGALS3, CD63, and others), and recruitment of phagocytes (APOE, CHI3L1, LGALS3, and others)." (PMID 32723919, 2020). "Cellular depletion of CD63 or treatment of cells with CD63 antibodies leads to decreased infectivity of HIV-1, HCV, LUJV, and oncogenic HPV types presenting CD63 as a more general mediator of virus infection." (PMID 29887866, 2018). "Of the 33 human Tspans, CD151, CD82, CD81, CD63, CD9, Tspan9, and Tspan7 have been associated with viral infections." (PMID 29887866, 2018). "Moreover, CD63 has been extensively studied as a general mediator of virus infection, including the human papillomavirus, human immunodeficiency virus-1, and hepatitis C virus." (PMID 34645935, 2021). "Importantly, the CD63-GY→AA mutant was unable to support HPV infection thereby suggesting that the CD63-dependent step in virus infection relies on the endosomal CD63 protein pool." (PMID 27578500, 2016). "It is known that CD81 participates, in concert with other tetraspanins, like CD63 and CD9, in many biological processes such as cell adhesion, migration, cell–cell fusion as well as in multiple steps of viral infection, especially in the case of HIV-1." (PMID 36988579, 2023). "Among all the cell surface proteins, Cluster of Differentiation (CDs such as CD9, CD63, CD81, CD151, CD82) and Tetraspanin (Tspan) types that includes Tspan7 and Tspan9 have been reported to be involved in viral infections." (PMID 33968023, 2021). "This is in line with previous studies demonstrating that CD63 and CD151 are involved in HPV and HCMV infection and that the C-terminal domains of these tetraspanins are indispensable for their role in virus infection." (PMID 30279342, 2018). "However, studying the biogenic proteins of exosomes in viral infections is crucial because tetraspanins, such as CD81, CD63, and CD9, are involved in viral release and regulate the increase in exosome production." (PMID 40572291, 2025). "When considering the effect of CD63 (and to some extent CD9) depletion on viral infection, our results might appear surprising at first sight." (PMID 37198427, 2023). "CD81, CD63, and CD9 signals on CSF EVPs were significantly decreased in the viral disease group (p = 0.005, p = 0.0151, and p = 0.0050, respectively) compared to the non-viral disease group, although this trend is likely heavily influenced by the HAM patient CSF EVPs (open blue circles)." (PMID 37622115, 2023). "Patients with certain autoimmune conditions and viral infections are known to exhibit increased circulating monocyte aggregates (in both the presence and absence of platelets), which are characterized by an overexpression of SELL and CD63, among other markers." (PMID 34721400, 2021). "What is also interesting is that CD63 can regulate EVs and HSV-1 secretion during virus infection." (PMID 32290097, 2020).
viral infection (continued). "However, WT virus infection failed to further induce CD63 exocytosis in CIN85 KD cells compared to parental cells." (PMID 40990523, 2025). "The elevated CD63 transcripts could also represent a host reaction to the viral infection rather than an intended outcome of the virus." (PMID 34190582, 2021). "We examined whether autophagy induction or inhibition through small molecule drugs alters the expression of CD63-GFP without any viral infection." (PMID 33922397, 2021).
Sepsis (18 papers, 2015 to 2025). Sepsis is defined as life-threatening organ dysfunction caused by a dysregulated host response to infection. "Recent studies have found that elevated exosomal CD63 levels are associated with the severity of organ failure and predict the mortality of severe sepsis patients." (PMID 39262873, 2024). "The presence of the exosome markers CD81 (tumor susceptibility gene), TSG101and CD63 was confirmed in both the sham and sepsis samples by Western blotting analysis, indicating the isolated particles were exosomes." (PMID 37256132, 2023). "We also observed the associations between CD66b+/CD63+ neutrophil-derived BAL EV in patients with sepsis and increased BAL IL-8 concentration and decreased alveolar macrophage efferocytosis." (PMID 35234046, 2022). "In summary, exosomal CD63 levels were associated with the severity of organ failure and predictive mortality in critically ill patients with sepsis." (PMID 34645935, 2021). "Nonetheless, the association of exosomal CD63 with the severity and mortality of sepsis is not well known." (PMID 34645935, 2021). "Elevated levels of exosomal CD63 were associated with the severity of organ failure and predictive of mortality in critically ill patients with sepsis." (PMID 34645935, 2021). "Finally, we tried to explain that CD63 is involved in immune and inflammation responses to infection and associated with sepsis severity and mortality through the results of previous studies." (PMID 34645935, 2021). "Compared with other studies, the overall level of exosomal CD63 in sepsis patients was associated with organ failure and mortality in this study, thus suggesting its possibility as a biomarker for the assessment of the severity and for the prediction of mortality owing to sepsis." (PMID 34645935, 2021). "Therefore, in the present study, the overall levels of exosomal CD63 were evaluated to ascertain whether they were associated with organ failure and mortality in patients with sepsis." (PMID 34645935, 2021). "Therefore, we assessed the levels of exosomal CD63 in sepsis patients and evaluated whether these were associated with organ failure and mortality." (PMID 34645935, 2021). "Although quantification of exosomal CD63 may be an advantage and the point of differentiation in our study, additional studies, including other tetraspanins, could strengthen the analysis and diagnostic potential of tetraspanins in sepsis." (PMID 34645935, 2021). "This indicates that, as expected, the increased sepsis levels of CD63 compared to SIRS largely stem from immature granulocytes but that PLAC8 expression is additionally increased in PMNs." (PMID 39434093, 2024). "The granule biogenesis pathway genes CEACAM4, PLAC8, and CD63 were analyzed by quantitative real-time polymerase chain reaction (qRT-PCR) and their abilities to distinguish sepsis and SIRS were compared to the routine infection marker CRP (C-reactive protein)." (PMID 39434093, 2024). "In the LD granulocytes by contrast, the sepsis-SIRS differences in CD63 and PLAC8 expression were comparable." (PMID 39434093, 2024). "In sepsis patients and upon neutrophil activation in vitro, CD63 becomes detectable at the cell surface." (PMID 39434093, 2024). "But using the levels of CEACAM4 in the HD fraction as a reference for PLAC8, also a SeptiCyteTM LAB gene, and CD63 in the LD fraction still improved the sepsis-SIRS distinction by these two azurophilic granule genes compared to their unreferenced LD levels." (PMID 39434093, 2024). "The analysis of flow cytometry experiments demonstrated that a significant portion of vesicles was positive for CD63 and CD11b in sepsis patients compared to healthy volunteers, suggesting an exosomal and monocyte origin for these vesicles." (PMID 37537685, 2023). "Further studies, including biogenetic mechanisms and functional studies of exosomal CD63 would provide helpful clues for the development of new targeted treatment based on exosomal CD63 modulation in sepsis." (PMID 34645935, 2021).
Sepsis (continued). "The strength of our study is attributed to the capacity to quantify exosomal CD63 in a larger cohort of critically ill patients with sepsis." (PMID 34645935, 2021). "On this subject, we aimed to analyze the relationship between exosomal CD63 and severity and mortality of sepsis in humans." (PMID 34645935, 2021). "Trends of increased exosomal CD63 levels were observed in control, sepsis, and septic-shock groups (6.6 μg/mL vs. 42 μg/mL vs. 90 μg/mL, p < 0.001)." (PMID 34645935, 2021). "In this regard, the utility of CD63 as a biomarker for diagnosis and prognosis of sepsis has been a particular field of interest." (PMID 34645935, 2021). "Exosomal CD63 was measured from prospectively enrolled critically-ill patients with sepsis (n = 217) and healthy control (n = 20)." (PMID 34645935, 2021). "Reduction of CD63 increases the mortality rate of sepsis in mice through its function in the immune response." (PMID 32174955, 2020). "After LPS stimulation, the sepsis group had higher levels of CD63 and CD35 surface expression than those of the volunteer group." (PMID 32733440, 2020). "Neutrophil activation marker CD63 was upregulated in patients with sepsis, suggesting that circulating neutrophils are fully activated in sepsis." (PMID 26063982, 2015). "Additionally, we utilized engineered EVs containing GFP to assess the distribution of ADMSC-EVs in sepsis-induced mice, producing a plasmid named “CD63-GFP” to generate ADMSC-EVsGFP, consistent with prior research." (PMID 41143725, 2025). "Interestingly, unreferenced PLAC8 showed the largest and CD63 the smallest sepsis-SIRS difference in total granulocytes, whereas for both genes the sepsis-SIRS differences in the LD fractions were comparable." (PMID 39434093, 2024). "The study combined in vitro measurements of toxin-induced thrombocyte activation assessed as increased membrane abundance of P-selectin, fibronectin and CD63 and data from in vivo murine model of sepsis-induced by HlyA-producing E. coli under infusion of P2Y1 and P2Y12 antagonists." (PMID 32781764, 2020). "Likewise, CD63 was also largely induced in TREM2+ monocytes of sepsis patients." (PMID 39405126, 2024). "However, sepsis/septic shock could also directly increase CD63; the mechanism of increased CD63 levels in the exosomes of critically ill patients is still unclear." (PMID 34645935, 2021). "Compared with sepsis normal-density neutrophils (NDN), sepsis-LDN demonstrated higher expression of CD66b, CD63, CD11b, and CD184, but lower expression of CD62L and CD182 and defects of effector functions, including phagocytosis and apoptosis." (PMID 40108283, 2025). "By qRT-PCR, the azurophilic granule genes CD63 and PLAC8 showed higher sepsis than SIRS levels in LD granulocytes and PLAC8 also in total granulocytes where its discriminatory performance resembled C-reactive protein (CRP)." (PMID 39434093, 2024). "Higher expression levels of CD63 and PLAC8 in sepsis than SIRS reached statistical significance in both total and LD granulocytes." (PMID 39434093, 2024). "Biomarkers of sEVs (CD63, CD9, CD81, Alix, and Tsg101) isolated from healthy control subjects and patients with sepsis were detected using western blotting." (PMID 38910259, 2024). "A positive correlation between exosomal CD63 and SOFA scores was observed in patients with sepsis (r value = 0.35; 95% confidence interval (CI) 0.22–0.46)." (PMID 34645935, 2021). "A positive correlation between exosomal CD63 and SOFA scores was observed in patients with sepsis (r value = 0.35)." (PMID 34645935, 2021). "The EVs expressed typical exosomal (CD63 and CD9) and epithelial (EpCAM) markers, which were further increased by sepsis." (PMID 33182773, 2020). "The basal expression levels of CD63 and CD35 were significantly increased in the sepsis group compared with those in the volunteer group." (PMID 32733440, 2020). "Expression of the tetraspanins CD63 and CD9 from large intestine lavage EVs was upregulated during sepsis." (PMID 33182773, 2020).
Sepsis (continued). "Another study which evaluated leukocyte activation in sepsis showed that cell surface expression of all activation markers (CD11b, ICAM-1, CD66b, CD63, and CD64) was increased on both neutrophils and monocytes from sepsis patients compared to healthy controls." (PMID 26063982, 2015). "Sepsis-induced LDNs can partly be generated by the induction of endotoxemia; however, some characteristics of LDN-sepsis (CD63, CD184, and PD-L1) might be induced by other factors." (PMID 40108283, 2025). "However, LPS-LDN (in vitro LDN) showed lower expression of CD63, CD184, and PD-L1 compared with LDN from patients (sepsis-LDN), suggesting a partial LPS impact on LDN generation." (PMID 40108283, 2025). "Heatmaps revealed that the expression levels of CD63, CD9, CD81, Tsg101, EEA1, Rab5, and Rab7 in lung macrophages were significantly higher than those in neutrophils in the healthy control sEV group and sEVs from patients with sepsis." (PMID 38910259, 2024). "To determine whether these particles could be EVs produced by the CP, similar to what we described in sepsis, we analyzed the expression of several EV markers, namely ALIX, ANXA2, CD63, FLOT1 and RAB5, in brain samples from early stage AD mice compared to WT age-matched control mice." (PMID 34425919, 2021). "Across all patients with sepsis, with and without ARDS, CD66b+/CD63+ BAL EV correlated inversely with alveolar macrophage efferocytosis index (r = −0.612, P = 0.0025)." (PMID 35234046, 2022). "Across all patients with sepsis, with and without ARDS, CD66b+/CD63+ BAL EV correlated directly with BAL interleukin (IL)-8 concentrations (r = 0.751, P < 0.0001)." (PMID 35234046, 2022). "The level of exosomal CD63 was higher among patients with septic shock (90 μg/mL, IQR 49–140 μg/mL) compared with healthy controls (6.6 μg/mL, IQR 4.8–11 μg/mL) and sepsis patients without shock (42 μg/mL, IQR 22–90 μg/mL, p < 0.001)." (PMID 34645935, 2021). "Taken together, this indicates that elevated expression of CD63 but not PLAC8 in sepsis is restricted to LD granulocytes and that a concomitant reduction of CEACAM4 expression in HD granulocytes improves the ratiometric discrimination between sepsis and SIRS." (PMID 39434093, 2024).